CRP (C-reactive protein)
Diseases named in the same sentence as CRP in open-access papers (continued):
Sharing a sentence is not in itself a finding about the gene and the disease.
diabetes (continued). "Most of the features of the so-called metabolic syndrome, including obesity, higher levels of triglycerides, diabetes, ischemic heart disease, arterial hypertension and elevated serum levels of C-reactive protein and fibrinogen, were clustered in this COPD subtype." (PMID 25153331, 2014). "C-reactive protein, a biomarker of inflammation, has been established as a risk marker and may exacerbate peripheral arterial disease, and C-reactive protein levels tend to be elevated among those with diabetes." (PMID 24967220, 2014). "In Danish type 1 diabetes, higher level of CRP was evidenced to be associated proliferative diabetes retinopathy, but this was no longer statistically significant after adjustment for diabetes duration and glycemic level." (PMID 24835219, 2014). "These individuals tend to have higher CRP concentrations than those without diabetes, and elevated CRP in diabetes is associated with increased risk of non-fatal cardiovascular events and cardiovascular death." (PMID 25192283, 2014). "In our study, there were more diabetes patients and higher C-reactive protein in ISR group may be related to inflammatory mechanisms." (PMID 25427155, 2014). "Our aims were to evaluate whether diabetes increases CRP expression in arterial macrophages and to study a possible correlation between CRP expression in human monocytes derived macrophages (HMDM) and CRP content in carotid atherosclerotic plaques." (PMID 24588988, 2014). "Diabetes up-regulated carotid plaques CRP levels and CRP measurements in HMDM could reflect atherosclerotic lesion macrophages secretion of CRP." (PMID 24588988, 2014). "The association trends between retroperitoneal fat, metabolic profiles, adipokine concentrations, CRP concentrations, and incident hypertension and diabetes were similar to those of peritoneal fat, but differed from those of subcutaneous fat in the present study." (PMID 25401949, 2014). "After adjusting for age, BMI, WC, TC, HCL-C, log-TG, alcohol intake status, smoking status, physical activity, follow-up period, and log-CRP, the ORs for incidence of diabetes according to GGT quartile were 1.00, 1.86, and 1.97 in males and 1.11, 1.60, and 2.45 in females." (PMID 24502834, 2014). "Baseline PEDF was independently associated with CKD progression (hazard ratio = 2.76; 95% confidence interval = 1.39–5.47; P = .004), adjusted for age, sex, waist circumference, diabetes duration, hemoglobin A1c, systolic blood pressure, use of antihypertensive drugs, C-reactive protein, and eGFR." (PMID 25166721, 2014). "The results of our study agree with the findings of previous investigations in that the baPWV was associated with factors such as older age, hypercholesterolemia, diabetes mellitus, cigarette smoking, higher blood concentration of C-reactive protein, and presence of a metabolic syndrome." (PMID 25225895, 2014). "However, the relationship between HRV and PWV is no longer significant with the addition of either HR (Model 3d) or CRP (Model 3e) to the age-adjusted model or age and diabetes adjusted model (Model 4d, e)." (PMID 24356038, 2014). "We hypothesized that CRP could be locally secreted in the atherosclerotic lesion by arterial macrophages and that pro-atherosclerotic triggers such as diabetes could up-regulate atherosclerotic lesion secretion of CRP." (PMID 24588988, 2014). "In patients with Type 2 diabetes mellitus (DM), the level of systemic inflammation, measured by C-reactive protein (CRP), may be a predictor of cardiovascular disease (CVD) and worse prognosis." (PMID 25163828, 2014). "After adjusting for age, BMI, WC, TC, HDL-C, log-TG, alcohol intake status, smoking status, physical activity, follow-up period, and log-CRP, the ORs for incidence of diabetes according to ALT quartile were 1.53, 2.24, and 2.31 in males and 0.97, 1.38, and 1.86 in females." (PMID 24502834, 2014).
diabetes (continued). "However, after adjustment for various potential confounders, the independent predictors of poor outcome in patients with BAD were CRP and smoking, while diabetes mellitus became insignificant." (PMID 24039853, 2013). "Regardless of hs-CRP levels, both diabetes mellitus and hypertension appeared to be associated with a lower incidence of CAS in women and men." (PMID 24204905, 2013). "SBP, serum albumin, CRP were significantly associated with microalbuminuria (p value for uric acid was 0.068) while additional risk factors including total cholesterol, ALT, cystatin C and diabetes were significantly associated with overt albuminuria." (PMID 23947772, 2013). "In addition, male gender, age, diabetes mellitus, BMI, and triglyceride, LDL-C, hs-CRP, and uric acid levels were associated with cf-PWV." (PMID 24312587, 2013). "Although the associations between C-reactive protein and CAD is similar across diabetes status and C-reactive protein is an independent prognostic marker of CAD, the roles C-reactive protein play in CAS development in diabetic patients and in predicting prognosis of CAS have not been evaluated." (PMID 24204905, 2013). "An additional important contribution of this study is that after adjusting for confounders including BMI, smoking status, race, gender, hypertension and diabetes, IL-6 and CRP, which are two key markers of chronic inflammation, showed association with oral health conditions." (PMID 23950871, 2013). "In addition, several cross-sectional studies have shown an increase of CRP levels in patients with diabetes and the increase of CRP, IL-6, and TNF-alpha in subjects with IGT." (PMID 23690772, 2013). "High PTX3, PCT, age over 60 years, alcohol abuse, diabetes and continuous systemic cortisone treatment were associated with case fatality (d28) in the univariate model while the level of CRP was not (data not sown)." (PMID 23341967, 2013). "Therefore, we sought to identify the roles that gender, high-sensitivity C-reactive protein (hs-CRP), diabetes mellitus and hypertension play in CAS development and prognosis." (PMID 24204905, 2013). "As various parameters, like CRP, diabetes, and age differed significantly between our patients with high and low PLR these parameters might affect our results although we adjusted these results for confounding factors in a regression analysis." (PMID 23844064, 2013). "Moreover, chronic subclinical inflammation is associated with prediabetic state and a significant lineer increase in incidence of new diabetes with increasing quartiles of hs-CRP." (PMID 24353563, 2013). "Although having diabetes was associated with high CRP, as expected, diabetes status by n-3 intake was not a significant predictor of high CRP (p=0.132)." (PMID 31667003, 2013). "Moreover, the significant correlations between hs-CRP and diabetes and airway diseases such as chronic obstructive pulmonary disease and asthma have been reported." (PMID 24381758, 2013). "C-reactive protein is occasionally elevated in patients with diabetes mellitus." (PMID 24204905, 2013). "Our finding that men but not women with diabetes mellitus who have low hs-CRP levels are at high risk of developing CAS indicates that gender differences in vascular reactivity also extend to the diabetic state." (PMID 24204905, 2013). "Measurement of subclinical inflammatory markers like CRP might improve the prediction of cardiovascular disease and diabetes in depressed patients with MTB." (PMID 24170724, 2013). "Patients in both two topographically identified groups with good outcome had a significantly lower level of CRP (P<0.01) than poor outcome, and the incidence of diabetes mellitus (P = 0.033) was significantly more prevalent in the PPA group of patients with poor outcome." (PMID 24039853, 2013).
diabetes (continued). "Elevated TnI was associated with adjusted HR for all-cause mortality of 2.57 (95% CI 1.30-5.09) and an adjusted HR for cardiac death of 3.14 (95% CI 1.07-9.2), after accounting for age, time on dialysis, diabetes status, prior coronary artery disease history, and C-reactive protein." (PMID 24206774, 2013). "Out of nine tested parameters (age, duration of diabetes, systolic and diastolic blood pressure, albumin excretion rate, serum HbA1c, CRP, TGF-β1, and creatinine), it turned out that TGF-β1 in serum had the most discriminative power in predicting the occurrence of DR in juvenile patients with T1DM." (PMID 23671881, 2013). "As CRP was found to induce NF-κB activation in rat vascular smooth muscle cells and bovine aortic endothelial cells, treatment with quercetin in this work prevented NF-κB activation in both models of diabetes." (PMID 23717483, 2013). "For the clustering of CRFs where stage 2 hypertension, high CRP, obesity, diabetes and smoking were aggregated, we found that the likelihood of mobility limitation increased linearly with increasing number of CRFs, when adjusting for demographics and APOE genotype (model 1)." (PMID 23741513, 2013). "Next, we measured the expression of CRP, which was increased by alloxan-induced diabetes." (PMID 23737649, 2013). "In addition, supplementation with α-tocopherol resulted in decreased circulating IL-1β, IL-6, TNF-α, and CRP in individuals with diabetes." (PMID 23158971, 2012). "Mean C-reactive protein in participants with diabetes was 5.8 mg/L." (PMID 22863308, 2012). "The most important risk factors of MIH and restenosis are ischemia/reperfusion injury, shear stress, inflammation, diabetes, oxidative stress, hypertension, modulation of cytokine, and C-reactive protein [CRP] level, together with other environmental stimuli such as smoking." (PMID 22489270, 2012). "In diabetes, some recent studies have demonstrated the role of physical training in reducing CRP." (PMID 22566996, 2012). "GFR < 45 ml/min/1.73 m2, age ≥ 61 years, CVD, diabetes, CRP ≥ 5 mg/L, Hb ≤ 110 g/L, p-albumin ≤ 35 g/L and overweight were all associated to impaired HRQoL, indicating that HRQoL related to renal function level, as well as to other conditions associated to CKD, like inflammation and CVD." (PMID 22710013, 2012). "Physical activity (of both moderate and vigorous intensity) is inversely associated with the quantitative CRP levels in serum, independent of diabetes and body adiposity." (PMID 22524121, 2012). "Considering the different categories of physical activity, there was a significant inverse correlation between quantitative CRP and higher physical activity in both men and women after multiple adjustments for age, residential area, BMI, waist-circumference, smoking, and diabetes mellitus." (PMID 22524121, 2012). "Furthermore, the results confirm the effect of obesity and diabetes on circulating levels of CRP described by other authors." (PMID 23049543, 2012). "Similarly, for CVD/diabetes mortality, health behaviors and health status had the largest mediating effects, 21% and 18%, respectively, while health insurance and CRP each accounted for only a small portion of the low-income disparity." (PMID 23185488, 2012). "The OR for poor functional outcome was greater in the highest tertile (5.73, P = 0.03) than in the lowest tertile of D2 YKL-40 in AIS patients after adjusting for age, sex, hypertension, diabetes mellitus, hypercholesterolemia, smoking, previous stroke and D2 CRP level." (PMID 23272150, 2012). "CRP is an indicator of the inflammatory status of recognized importance in relation to cardiometabolic alterations, with independent predictive value for incident diabetes and cardiovascular diseases." (PMID 22472183, 2012). "There is also evidence supporting the suggestion that CRP levels are increased in diabetes." (PMID 22701277, 2012).
diabetes (continued). "The univariate conditional logistic regression analysis showed a significantly increased risk of incident T2DM for family history of diabetes, hypertension, systolic and diastolic blood pressure, FPG, 2hPG, BMI, triglycerides, CRP, tPA, PAI-1, tPA/PAI-1 complex, and VWF." (PMID 23249721, 2012). "With regard to the inflammatory biomarkers, participants with incident diabetes had higher baseline levels of CRP, fibrinogen, interleukin-6, urinary isoprostanes, lipoprotein-associated phospholipase A2 mass, monocyte chemoattractant protein-1, P-selectin, and tumor necrosis factor receptor." (PMID 23130155, 2012). "Whether reduction of CRP will be observed among patients with high baseline CRP and followed over a long period as in the ACCORD (Action to Control Cardiovascular Risk in Diabetes) study is yet to be determined." (PMID 21939559, 2011). "Hazards ratios are adjusted for age, sex, previous CVD events, diabetes mellitus and time-dependent type of renal replacement therapy (Model 1) and an extended adjustment additionally for albumin, CRP, current smoking, native fistula and ejection fraction (Model 2 as sensitivity analysis)." (PMID 21408188, 2011). "Uric acid levels were negatively associated with duration of diabetes, fasting plasma glucose, glycohemoglobin, eGFR, HDL-cholesterol (all P < 0.001) and positively with BMI, CRP, waist circumference, triglycerides, systolic blood pressure, ACR, HOMA-IR and IMT (all P < 0.05)." (PMID 21816063, 2011). "Soluble ST2 levels have also been found elevated in numerous inflammatory disorders which are thought to exert a protective effect and from this point of view the correlation of sST2 levels with CRP levels in diabetics in our study most possibly reflects the inflammatory component of diabetes." (PMID 22104207, 2011). "Chronic kidney disease patients were older, 81% (n = 951) had albuminuria, had a higher prevalence of diabetes mellitus, hypertension, cardiovascular disease, higher body mass index, higher CRP levels, and lower smoking exposure compared to participants without CKD." (PMID 21569369, 2011). "Analysis was performed for associations with the following risk factors: diabetes, HbA1c, age, BMI, waist circumference, waist-hip ratio, total cholesterol, triglyceride, HDL cholesterol, C-reactive protein, homocysteine, blood pressure, heart rate, urine ACR, smoking status, alcohol abstinence." (PMID 21029470, 2010). "We aimed to investigate whether CRP was mediating the association between HNF1A G319S and type 2 diabetes in an Aboriginal Canadian population with a high prevalence of diabetes." (PMID 20716378, 2010). "Using a large, population-based cohort, our study replicated all previous associations of the GCKR rs780094 polymorphism with metabolic traits, including fasting glucose, insulin, post-OGTT glucose, CRP, and triglyceride concentrations and diabetes prevalence among white participants." (PMID 20661421, 2010). "A stratified analysis by the WC levels was, thus, performed to check whether the association between the CRP (or GGT) and diabetes was mediated through obesity." (PMID 21076541, 2010). "The negative associations seen in nonobese individuals could also be the result of an anti-inflammatory effect of diabetes medications in a population with generally lower adipose-generated levels of IL-6 and lower CRP." (PMID 20123638, 2010). "The results showed that the CRP was associated with the presence of diabetes only in obese women, not in women with low WC." (PMID 21076541, 2010). "Our observations among Peruvians suggest that chronic systemic inflammation, as evidenced by elevated CRP, may be of etiologic importance in insulin resistance and diabetes." (PMID 20482756, 2010). "Second, some studies have shown that CRP, a sensitive marker of chronically subclinical inflammation, emerged to be part of the insulin resistance syndrome and an important factor in the pathogenesis of diabetes." (PMID 21076541, 2010).
diabetes (continued). "In summary, CRP levels were lower in HNF1A S319 allele carriers compared to non-carriers among Aboriginal Canadians without diabetes, but this difference was not present among those with prevalent type 2 diabetes, a group with markedly elevated CRP levels." (PMID 20716378, 2010). "Hs-CRP did not vary by to diabetes status, but was strongly associated with both waist circumference and BMI." (PMID 20617007, 2010). "After adjustment for age, smoking, diabetes status and medication use (NSAID, cholesterol, hypertension and depression medications), MLR revealed that WC, BMI, and gender were all significantly associated with ln hs-CRP (P < 0.05)." (PMID 20617007, 2010). "In this sample of Cuban-Americans, WC and BMI had stronger associations with ln hs-CRP but not with diabetes status." (PMID 20617007, 2010). "Approximately 60% of high CRP in Busselton could be attributed to smoking, body mass index (BMI), blood pressure, diabetes, total cholesterol, triglycerides and low HDL cholesterol." (PMID 21078191, 2010). "Cross-sectional and longitudinal studies have shown a positive association between the CRP and diabetes in women but not in men." (PMID 21076541, 2010). "Based on these findings, the authors argued that variation in genes including HNF1A may have subsequent impact on vascular disease and diabetes influenced or marked by circulating CRP concentrations." (PMID 20716378, 2010). "Obesity prevention and controlling for CRP levels may be necessary to eliminate its contributions to develop diabetes and cardiovascular disease (CVD)." (PMID 20617007, 2010). "The current study provides evidence that variation in HNF1A is associated with variation in CRP in diabetes-free individuals (although not in those with diabetes) in populations other than European Caucasians." (PMID 20716378, 2010). "Females exhibited a strong association for both waist circumference and BMI with hs-CRP, regardless of diabetes status." (PMID 20617007, 2010). "Collectively, available evidence suggests that systemic inflammation, as evidenced by elevated CRP, may be of etiologic importance in insulin resistance and diabetes." (PMID 20482756, 2010). "For men without diabetes the association between waist circumference and BMI with hs-CRP was much stronger than for men with diabetes." (PMID 20617007, 2010). "A similar association was revealed for BMI and ln hs-CRP, with males without diabetes showing a stronger relationship (B = 0.127, P < 0.001) than with diabetes (B = 0.020, P = 0.458)." (PMID 20617007, 2010). "Among individuals with diabetes who are likely under chronic inflammatory stress, however, another mechanism may be modulating increased circulating CRP." (PMID 20716378, 2010). "CRP has been identified in many previous studies as a poor prognostic factor in several diseases, including coronary artery disease, chronic obstructive pulmonary disease, diabetes mellitus, myeloma bone disease, and a variety of cancers." (PMID 19457231, 2009). "In the Cardiovascular Health Study, CRP was significantly associated with diabetes in nearly 190 subjects who never smoked, but not in nearly 180 subjects who had smoked." (PMID 22505974, 2009). "The serum CRP level was reported to increase in metabolic syndrome and diabetes." (PMID 19222849, 2009). "CRP has been shown to be related to future cardiovascular events, and this was also true in our study, even after adjustment for potential confounders such as smoking, hypertension, hyperlipidemia, BMI, and diabetes mellitus." (PMID 18518944, 2008). "In a nested case-control study, AST, ALT, GGT as well as classic diabetes risk factors, insulin and C-reactive protein (CRP) were measured in 133 non-diabetic subjects at baseline of which 68 were cases and 65 were controls." (PMID 18533046, 2008).